IL6 (interleukin 6)
Diseases named in the same sentence as IL6 in open-access papers (continued):
Sharing a sentence is not in itself a finding about the gene and the disease.
COVID-19 (continued). "In fact, IL-6 and the inflammatory marker C-reactive protein (CRP) have been reported to correlate with COVID-19 symptoms." (PMID 35529699, 2022). "Increased plasma levels of pro-inflammatory cytokines and chemokines (especially IL-2, IL-6, IL-10, and TNF-α) with impaired IFN-I activation in severe COVID-19." (PMID 36072602, 2022). "A number of studies highlighted that elevation of IL-6 levels was correlated with adverse outcomes in SARS-CoV-2 infection, defined as severe COVID-19 occurrence, the requirement for mechanical ventilation, and death." (PMID 35185562, 2022). "Clinical studies have suggested that there is an elevation in the neutrophil infiltration in lung alveoli, and in systemic conditions, with total increment of IL-6 and CRP together with lymphopenia occur in COVID-19 patients." (PMID 35812188, 2022). "To date, only a small study with 24 patients has explored a combination model with IL-6, sKL-6, and CRP values to detect patients with severe COVID-19 with promising results." (PMID 36004366, 2022). "In patients with COVID-19 requiring intensive care, low CD4+ and CD8+ cell counts are also detected, negatively correlated with a high expression of cytokines (IL-6, IL-10, and TNF-α)." (PMID 35741174, 2022). "The uncontrolled release of IL-6, IFNγ, and TNF-α can result in a downstream cascade of cytokine and cellular responses that further contribute to disease severity in both COVID-19 and malaria." (PMID 36415655, 2022). "The severe COVID-19 group showed significantly higher CCL2 and IL-6 expression levels than the moderate COVID-19 group (P<0.001)." (PMID 35982898, 2022). "Therefore, increased CRP and IL-6 might be related to the disease severity of COVID-19." (PMID 35037900, 2022). "High IL-6 has been reported in serious diseases, including sepsis, acute respiratory distress syndrome (ARDS), and COVID-19." (PMID 36285159, 2022). "Analysis of cytokine and chemokine expression levels revealed higher IL-1β, IL-6, TNF, and CCL2, CCL3, CCL4, and CCL7 in severe COVID-19 BALF compared to moderate disease." (PMID 35401519, 2022). "In COVID-19 patients, HMGB1 can be released from dying cells and functions as a pro-inflammatory inducer to bind with TLR4, leading to the production of IL-1β, IL-6, and TNF-α." (PMID 35832809, 2022). "Thus, inhibition of IL-6 pathway may be beneficial to patients with severe COVID-19." (PMID 36182930, 2022). "Altogether, our results are indicative of the importance of the hsa_circ_0000479/hsa-miR-149-5p/IL-6, RIG-I pathway in COVID-19." (PMID 36081604, 2022). "Evidence suggests that the level of interleukin-6 (IL-6) is more accurate than the C-reactive protein (CRP) and other inflammatory indicators in expecting respiratory failure in COVID-19." (PMID 36558489, 2022). "IL-6 levels in severe COVID-19 patients are significantly higher than in other patients, prompting several researchers to recommend TCZ to inhibit IL-6 signaling in patients with severe COVID-19 to improve patient symptoms." (PMID 35784318, 2022). "More detailed studies are needed about the HPA axis in diabetic patients with COVID-19 and detailed molecular studies evaluating the ACTH, cortisol pulsatile secretion, and cortisol-IL-6 relationship." (PMID 36016249, 2022). "Correlations between NP and CRP, or between NP and IL-6 in COVID-19 patients were weaker than that between CRP and IL-6." (PMID 35529699, 2022). "The death-to-live ratio of COVID-19 patients was 457:43 indicating that the patients having elevated levels of both CKMB, D-dimer, CK and IL-1, IL-6, IL-10 and D-dimer, Troponin, CK and IL-1, IL-10 had high fatality rate (73% and 12% respectively)." (PMID 36298704, 2022). "Off-label use of plenty of immunomodulatory drugs emerged, targeting cytokines involved in COVID-19 acute respiratory distress syndrome (ARDS), where high IL-6 levels have a prominent role." (PMID 35280907, 2022).
COVID-19 (continued). "Levels of Interleukin-6 (IL-6), c-reactive protein (CRP), procalcitonin, ferritin, and leukocytes were compared between COVID-19, other viral respiratory infections, and bacterial pneumonia." (PMID 35622838, 2022). "AhR/Kyn binding boosts the production of Interleukin-6 (IL-6), thus reinforcing the inflammatory state and counteracting the IDO-dependent immune tolerance in the later stage of COVID-19." (PMID 35203299, 2022). "In patients with MIS-C, it has been identified the cytokine storm with high concentrations of IL-1β, IL-6, IL-10, TNF-α, and especially IFN-γ, as an antiviral cytokine, comparatively to healthy controls or the children with acute COVID-19." (PMID 35887067, 2022). "The NF-κB pathway is shown to be involved in the pathogenesis of COVID-19 patients, as well as in the CSS, by inducing the expression of proinflammatory genes, including IL-6, chemokines, and growth factors, critical for the development of various diseases." (PMID 35408447, 2022). "Increased circulating levels of the pro-inflammatory cytokines IL-1β, IL-6, IL-8, and TNF-α are hallmarks in the immunopathology of chronic inflammatory diseases, including COVID-19." (PMID 35563697, 2022). "Severe cases of COVID-19 develop cytokine storms characterized by excessive systemic release of multiple cytokines including IP-10 (CXCL10), IL-6, IL-8 (CXCL8), and IL-10." (PMID 35247068, 2022). "Targeted inhibition of IL-6 and PAI-1 signal transduction appears to improve treatment outcomes in severely and critically ill COVID-19 patients suffering from cytokine storms and venous thrombosis." (PMID 35784318, 2022). "Seven out of the 16 known cytokine markers (including IL1A, IL1R1, CCL2, IL6, IL10, CXCL10, and VEGFA) were less pronounced in KD than in severe COVID-19 patients compared to FC and HC, respectively." (PMID 36159873, 2022). "Of the 16 mediators elevated in early COVID-19 compared with healthy controls, 11 decreased over time (CCL3, CCL4, TNF-α, IL-6, CCL13, IL-4, IFN-α2a, CXCL10, CXCL11, IL-2, and IL-12)." (PMID 35397798, 2022). "A similar hyper induction of proinflammatory cytokines, such as IL6, IL1B, and IFNG, was observed in COVID-19 patients, and the level of induction in these cases was proportional to the severity of the disease." (PMID 35740365, 2022). "Cytokines typical of Th2, Th9, Th17, and Tregs were either low or undetectable, although IL-6, IL-10, and IL-17A levels were higher in peptide-stimulated conditions compared with DMSO control conditions for convalescent COVID-19 participants." (PMID 35044955, 2022). "Two case reports describe decreasing IL-6 and CRP after onset of electrical VNS in four COVID-19 patients suffering from moderate or severe COVID-19-pneumonia." (PMID 36263035, 2022). "For IL-6, BALF macrophages of COVID-19 patients also exhibit elevated but generally lower response scores that are more scattered across subsets and have highest values in blood-derived monocytes." (PMID 35732153, 2022). "In the primary DILI sub-network of cluster 1, IL6, IL1B, TNF, and CCL2 were among the top ten key targets and related to the COVID-19 adverse outcome pathwaya inflammation of CRS exacerbated DILI." (PMID 35979235, 2022). "Levels of IL-6 and TNF-α in the serum can be considered for the COVID-19 patient treatment and management for the clinical trials, to guide resource allocation and therapeutic options." (PMID 36078094, 2022). "In COVID-19, IL-6 and CRP showed very high discriminative utility with an AUC of 0.899 (95%CI 0.850–0.948) for IL-6 and 0.922 (95%CI 0.879–0.946) for CRP, respectively." (PMID 35622838, 2022). "An increase in pro-inflammatory Th17 cells and lymphopenia associated with decreased CD4+ T cells, CD8+ T cells, and natural killer cells, and increased cytokine levels (IL-6, IL-10, and TNF-α) were observed in COVID-19 patients." (PMID 36353605, 2022).
COVID-19 (continued). "Higher levels of pro-inflammatory macrophages, neutrophils, and inflammatory cytokines, especially interleukin (IL)-6, IL-8, and IL-1β were conducted in the BALF of patients with severe/critical COVID-19." (PMID 36033885, 2022). "Of note, these cytokines (IL-6 and IL-8) were lower in HIV/COVID-19-coinfected individuals than in COVID-19 patients, suggesting a dampened inflammatory response to SARS-CoV-2 infection in immunocompromised subjects." (PMID 35891555, 2022). "High serum IL-6 and TNF-α levels are two strong and independent survival predictors of patient with COVID-19." (PMID 35356515, 2022). "A team studied the immune responses of 54 COVID-19 patients and found that TNF-α and IL-6 production by circulating monocytes was sustained." (PMID 35223745, 2022). "Serum levels of IFNγ, CRP, IL-10, IL-13, IL-6, IP10, MCP-1 and IL-23 were significantly higher in COVID-19 patients than in controls after adjustment for age and BMI." (PMID 36554094, 2022). "Six patients had moderate (n = 2, WHO score 4–6) or severe COVID-19 (n = 4, WHO score 7–10) requiring hospitalization and treatment with oxygen therapy (n = 5), corticosteroids (n = 5), and IL-6 monoclonal antibodies (n = 3)." (PMID 36240755, 2022). "Our study reveals that serum levels of interleukin (IL6), IL8, and surfactant protein-D (SP-D) can be used as early markers to stratify the severity of COVID-19, even on the day of hospitalization and before hypoxia sets in." (PMID 36518355, 2022). "The plasma levels of resistin, ICMA-1, IL-6, IL-10 and MCP-1 of the patients with sepsis were statistically higher than those of the patients with COVID-19 at all measurement points." (PMID 35784283, 2022). "As such, IL-6 may be a putative interlink of COVID-19/cancer interplay; however, it remains unclear whether the duration of the “cytokine storm”, presently known as an intense yet acute inflammatory phenomenon, would let enough time for IL-6 to exert its tumor-promoting effects." (PMID 36077865, 2022). "A COVID-19 study revealed the production of proinflammatory cytokines (CXCL-8, IL-6, CCL20, CCL3, CCL4, and IL-12) by dysfunctional mitochondria." (PMID 36092161, 2022). "Thus, the authors hypothesize that SARS-CoV-2 contains a large number of purU-rich sequences and can potentially hyperactivate TLR8-mediated inflammation, resulting in the marked elevations of TNF-ɑ, IL-6, fibrinogen, and blood viscosity observed in severe COVID-19." (PMID 35832759, 2022). "Our analysis show that the mean levels of IL-6 and TNF-α were significantly different in the study groups, with higher levels in COVID-19 patients and those residing at high altitude." (PMID 35090394, 2022). "IL-18, along with other cytokines (IFN-γ, IL-1, IL-6, TNF), are elevated in cytokine storm and are thought to have central immunopathologic roles in COVID-19." (PMID 36510222, 2022). "The levels of proinflammatory cytokines/chemokines such as interleukin 6 (IL-6), IL-8, interferon gamma (IFN-γ)-induced protein 10 (IP-10), and tumor necrosis factor alpha (TNF-α) are markedly elevated in the sera of severe COVID-19 patients (4, –, 9)." (PMID 35856559, 2022). "In the second publication, the serum levels of IL-6, TNF-alpha, and IL-8 were significantly elevated in COVID-19 patients, IL-6 being the most prominent cytokine (all in the order of magnitude of picogram/mL)." (PMID 36278528, 2022). "Based on a cohort of hospitalized COVID-19 patients with detailed records of cytokines, antibodies, and blood biomarkers, this retrospective study supports the hypothesis that early responses of elevated cytokines such as IL-6 may reflect active responses of the humoral immune system." (PMID 35248063, 2022). "There is plenty of evidence that elevated levels of different cytokines like IFN-γ, IL-6, IL-1β, IL-10 and MCP-1 are higher in COVID-19 patients." (PMID 36466830, 2022).
COVID-19 (continued). "IL-1α, IL-1β and ferritin were relatively increased in patients with COVID-19, particularly when compared with CAP-other and CAP-flu, whilst procalcitonin, IL-6 and CRP were highest in CAP-strep." (PMID 35660785, 2022). "A retrospective study that included 440 COVID-19 patients showed that the GDF15 serum level was increased and positively correlated with C reactive protein (CRP), IL-6 and IL-8 in severely affected patients." (PMID 36140453, 2022). "Several biochemical markers like C-reactive protein (CRP), interleukin-6 (IL-6), white cell count, lactate dehydrogenase (LDH), ferritin, albumin, and D-dimer predict COVID-19 outcome." (PMID 36084093, 2022). "The elevated levels of TNF α, IL-1RA, IL-6, IL-8, IL-10, IP-10, G-CSF and FGF-2 in both patient groups with COVID-19 in our study coincided with previously published studies." (PMID 36012146, 2022). "Neutrophil-lymphocyte ratio (NLR), C-reactive protein (CRP), interleukin-6 (IL-6), lactate dehydrogenase (LDH), D-dimer, ferritin, and CT thorax were done within 24h of admission before being initiated on any anti-COVID-19 therapy." (PMID 35382199, 2022). "Biomarkers related to COVID-19 severity, such as CRP, D-dimer, LDH, and IL-6 levels, were higher in patients in the severe group than in those in the non-severe group." (PMID 35816225, 2022). "This further increases IL-1, IL-6, and TNF-α secretions, and it contributes to COVID-19 post-infective acute myocarditis." (PMID 35464491, 2022). "Conversely, solid tumor patients that had elevated levels of inflammatory cytokines IL-6, CXCL8, and lost the coordinate production of anti-virus antibodies developed severe COVID-19 and died." (PMID 36700209, 2022). "COVID-19 patients had substantially greater levels of ACE2, IL-6, glucose, total white blood cells (WBCs), neutrophils, NLR, platelets, mean corpuscular hemoglobin (MCH), and mean corpuscular hemoglobin concentration (MCHC) than healthy participants." (PMID 36558489, 2022). "The use of vitamin E combined with vitamins A, C, B, and D, reduced ESR, CRP, IL-6, TNF-a, and hospitalization time in adults with COVID-19." (PMID 36295088, 2022). "Among the COVID-19 patients, HLH has become an unrecognized complication of an innate immune response by uncontrollable cytokine storm and enhanced quantity of IL-2, IL-6, IL-7, and TNF-α." (PMID 35165505, 2022). "Elevated IL-6 has been specifically highlighted as a contributor to pathogenesis during severe COVID-19 and IAV, and many efforts to block IL-6 signaling to improve disease outcomes are underway." (PMID 35512020, 2022). "Tension-type headache symptoms in patients with COVID-19 were positively correlated with inflammatory markers, CRP and IL-6." (PMID 35527821, 2022). "Significantly elevated levels of interleukin-6 (IL-6) and tumour necrosis factor-α (TNF-α) were found in the cerebrospinal fluid of patients affected by COVID-19." (PMID 36071466, 2022). "The PPI network analysis reveals that multiple targets, including IL-6, PPARG, MAPK3, PTGS2, ICAM1, MAPK1, etc., are involved in the anti-COVID-19 effects of Kochiae Fructus’ active phytomolecules." (PMID 35992697, 2022). "Subjects with the most severe form of COVID-19 (critically ill) had a lower concentration of Nrf2 that negatively correlated with the markers of hyperinflammatory response (CRP, IL-6, ferritin)." (PMID 36422196, 2022). "In the ongoing COVID-19 pandemic, damage to the mucosal barrier and immune cells due to the overproduction of pro-inflammatory (IL-1, IL-6, IL-12, IL-17, IFN-γ, TNFα) cytokines (cytokine storm) was evident in some COVID-19 patients." (PMID 36501067, 2022). "It was previously demonstrated that key plasma inflammatory markers (IL-6 and CRP) were significantly elevated in individuals with ongoing pulmonary sequelae of COVID-19 developed after the resolution of the acute phase." (PMID 36559025, 2022).
COVID-19 (continued). "In this study, the serum level of IL-6 and MIP-1α were found statistically significant (p < 0.001) among different COVID-19 patient groups." (PMID 35822078, 2022). "Leukocytosis, lymphopenia, elevated levels of C-reactive protein (CRP), procalcitonin (PCT), D-dimer, IL-6 (Interleukin-6), Neutrophil to Lymphocyte ratio (NLR), and Lactate dehydrogenase (LDH) have all been observed in COVID-19-infected cancer patients [,7]." (PMID 35127069, 2022). "Studies have shown that several circulating cytokines and chemokines such as TNFα, CXCL-10, IL-6, and IL-8 are differentially expressed during SARS-CoV-2 infection, and this cytokine/chemokine storm likely contributes to the poor prognosis of COVID-19." (PMID 34531741, 2021). "Many studies have reported an increase in IL-6, IL-1β, and CXCL-8 in severe patients with COVID-19, which are also important factors that induce granulocyte activation and NET release." (PMID 33557911, 2021). "Our study demonstrates that the levels of IL-6, IL-8, IL-10, VEGF, MCP-1 and EGF were significantly increased in the severe COVID-19 patients." (PMID 34868558, 2021). "The high concentration of COVA1-18 immune complexes elicited substantially less IL-1β, IL-6, and TNF than anti-spike immune complexes made from COVID-19 serum." (PMID 33979301, 2021). "The areas under ROC curves (AUROCs) were 0.868 for NLR, 0.811 for IL-6, 0.802 for IL-2R, 0.763 for IL-8, 0.731 for IL-10 and 0.699 for TNF-α when performing prediction of severe or critical COVID-19 cases." (PMID 34282057, 2021). "Toll-like receptor family members upregulated anti-viral and pro-inflammatory mediators (IL-6 and IL-8 and type I and type III interferons among others), through the activation of Nuclear Factor (NF)-kB in COVID-19." (PMID 34313585, 2021). "The level of these cytokines was also elevated in nasopharyngeal swabs of severe COVID-19 patients compared to healthy controls (for TNF-α, IL-1β and IL-1A, for IL-6, IL-8 and IL-23)." (PMID 33995033, 2021). "This is characterized by a fulminant increase in cytokine and chemokine levels including IL-2, IL-6, IL-7, IL-10, GCSF, IFN- γ, and TNF-α in patients with severe COVID-19." (PMID 33957949, 2021). "Since the IL-6, IL-8, CRP and platelet markers were significant predictors for COVID-19 severity, we further analyzed their correlations with other variables." (PMID 34488665, 2021). "In case of CVD + Cancer + CDK + COVID-19, the drugs and targets were lapatinib, gefitinib for EGFR, prednisolone for IL6, and AZD-1480, currently in a phase I/II trial for STAT3." (PMID 34067609, 2021). "NF-κB–dependent biomarkers including IL-6 and TNF superfamily mediators are increased in COVID-19 patients." (PMID 33232303, 2021). "Investigators discovered a negative correlation between T cell numbers and the concentration of cytokines including interleukin-6 (IL-6), IL-10, interferon-γ (IFN-γ), and tumor necrosis factor-α (TNF-α) in COVID-19 patients." (PMID 34766001, 2021). "We show that using Mylc lines, it is possible to detect the potential of sera from COVID-19 patients to enhance infection of SARS-CoV-2 and to augment IL-6 production." (PMID 34887501, 2021). "Patients with severe COVID-19 had significantly higher Gal-3, TNF-α, IL-1β, and IL-6 than those with moderate disease." (PMID 34367188, 2021). "Cytokine storm, which refers to the increased secretion of cytokines such as IL-1β, IL-6, TNF-α, and IL-18 is a characteristic of COVID-19 patients with lung damage." (PMID 34584616, 2021). "Among COVID-19 patients who have received ECMO, a strong positive correlation exists between mortality and high cytokine levels, most notably IL-6." (PMID 38624751, 2021). "IL-6 and TNF-α serum levels remained independent and significant predictors of disease severity and deaths of COVID-19 patients." (PMID 34834033, 2021).